CYP2J2 (cytochrome P450 family 2 subfamily J member 2)
Diseases named in the same sentence as CYP2J2 in open-access papers (continued):
Sharing a sentence is not in itself a finding about the gene and the disease.
folate deficiency (1 paper, 2017). A nutritional condition produced by a deficiency of FOLIC ACID in the diet. "Furthermore, tumor growth and size as well as patterns of CYP2J2 expression and DNA demethylation were increased with HHcy in mice induced orthotopically by 2% (wt/wt) L-methionine with or without folate deficiency." (PMID 28030819, 2017).
Glucose intolerance (1 paper, 2018). Glucose intolerance (GI) can be defined as dysglycemia that comprises both prediabetes and diabetes. "Moreover, glucose tolerance tests indicated that aging‐related glucose intolerance was suppressed significantly in 16‐month‐old CYP2J2‐Tr mice." (PMID 29318723, 2018).
kidney cancer (1 paper, 2021). Primary or metastatic malignant neoplasm involving the kidney. "Although the expression of CYP2J2 was elevated in a variety of cancers, it was found that elevated CYP2J2 expression levels were most significant in kidney cancer." (PMID 34258261, 2021).
kidney injuries (1 paper, 2022). "Additionally, it has been revealed that CYP2J2-produced epoxyeicosatrienoic acids protect against ischemia/reperfusion-induced kidney injuries by activating the SIRT1-FoxO3a signaling pathway." (PMID 35386302, 2022).
Myocardial fibrosis (1 paper, 2020). "Histological analysis indicate that cardiomyocyte-specific overexpressing CYP2J2 Tr mice were protected from pathological remodeling associated with MI injury while displaying significantly smaller infarct size and lower myocardial fibrosis compared to their WT counterparts." (PMID 32486275, 2020).
Parkinson disease (1 paper, 2025). A progressive degenerative disorder of the central nervous system characterized by loss of dopamine producing neurons in the substantia nigra and the presence of Lewy bodies in the substantia nigra and locus coeruleus. "CYP2J2 was found to be negatively enriched in the following four pathways: complement and coagulation cascades, toll like receptor signaling pathway, hematopoietic cell lineage, and cytoking cytoking receptor interaction, and positively enriched in Parkinsons disease." (PMID 41472876, 2025).
prostate carcinoma (1 paper, 2020). A carcinoma that arises from epithelial cells of the prostate gland. "A separate study observed CYP2C8, CYP2C9, and CYP2J2 mRNA and protein expression in prostate cancer derived cell lines." (PMID 32581794, 2020).
psoriasis (1 paper, 2020). An autoimmune condition characterized by red, well-delineated plaques with silvery scales that are usually on the extensor surfaces and scalp. "The aim of this study was to investigate CYP2J2 polymorphism in psoriasis, a chronic inflammatory skin disease that can be accompanied by cardiovascular diseases." (PMID 31902555, 2020). "This study investigated the possible role of CYP2J2 polymorphism as a risk factor in psoriasis patients." (PMID 31902555, 2020). "The results demonstrate a significantly higher frequency of T allele in psoriasis vulgaris patients and an increased risk of psoriasis in patients with CYP2J2 polymorphism in the dominant model." (PMID 31902555, 2020). "The present authors studied CYP2J2 polymorphism in psoriasis, a chronic inflammatory skin disease, and revealed an increased risk of psoriasis in patients with CYP2J2 polymorphism." (PMID 31902555, 2020). "CYP2J2 polymorphism has been identified as a risk factor for cardiovascular diseases, but its association with psoriasis remains unknown." (PMID 31902555, 2020). "CYP2J2 polymorphism may contribute to inflammatory process and pathogenesis of psoriasis through altering ETT concentrations, but to understand the psoriasis-CYP polymorphism-ETT relationship better, further studies are needed." (PMID 31902555, 2020).
pulmonary edema (1 paper, 2017). Accumulation of fluid in the lung tissues causing disturbance of the gas exchange that may lead to respiratory failure. "Thus CYP2J2-EETs is crucial for RhoA-dependent regulation of cytoskeletal architecture leading to reversible changes in vascular permeability, which may contribute to the development of new therapeutic approaches for pulmonary edema and other diseases caused by abnormal vascular permeability." (PMID 28881620, 2017).
tuberculosis (1 paper, 2024). A chronic, recurrent infection caused by the bacterium Mycobacterium tuberculosis. "In addition to its role in endogenous metabolism, recent studies highlighted the importance of CYP2J2 for metabolizing various drugs, including anti-malarial and anti-tuberculosis that are widely used in Africa39,40." (PMID 38778126, 2024).
Ventricular arrhythmia (1 paper, 2013). "Consistent with the in vivo results, large differences in ventricular arrhythmia susceptibility were also detectable in Langendorff preparations of perfused hearts isolated from WT and CYP2J2-TG mice 4 weeks after TAC." (PMID 24023684, 2013). "Conversely, the selective EET-antagonist 14,15-EEZE-mSi reversed the protection of hypertrophied CYP2J2-TG hearts against ventricular arrhythmia inducibility." (PMID 24023684, 2013). "Epicardial electrical stimulation induced ventricular arrhythmias in more than 90% of the protocols with the hypertrophied WT hearts compared with only 15% with the corresponding CYP2J2-TG hearts." (PMID 24023684, 2013).
cancer (40 papers, 2010 to 2025). A tumor composed of atypical neoplastic, often pleomorphic cells that invade other tissues. "CYP2J2 has also been found to be upregulated in a variety of cancers and associated with drug resistance." (PMID 36523635, 2022). "Elevated levels of CYP2J2 have been associated with various types of cancer, and therefore it serves as a potential drug target." (PMID 33682565, 2021). "CYP2J2 inhibitors such as C26 (1-[4-(vinyl)phenyl]-4-[4-(diphenyl-hydroxymethyl)-piperidinyl]-butanone hydrochloride) caused a marked reduction in tumor proliferation and migration as well as promoted apoptosis in cancer cells." (PMID 31998435, 2020). "Under pathological conditions, CYP2J2 and the metabolites derived from arachidonic acid play key roles in regulating cardiovascular function and malignant tumors." (PMID 40563315, 2025). "Another NIR fluorescent probe 3 was designed for real-time tracking of CYP2J2 in complex biological systems, leveraging the overexpression of CYP2J2 in various cancer cells." (PMID 38495994, 2024). "Several lines of evidence highlight the potential role of CYP2J2 and its mediated products in the cancer pathogenesis of many human tumors." (PMID 38001897, 2023). "CYP2J2 belongs to the cytochrome P450 family and is a gene of interest in numerous cancer types as a target for therapeutic inhibition." (PMID 36675007, 2023). "TsIIA exerts its anti-cancer effect directly by inhibiting CYP2J2 activity.The inhibition rate of TsIIA on CYP2J2 is (50%), IC50 is (2.5μM)." (PMID 36798821, 2023). "All of these effects were reversed in both in vitro and in vivo models via treatment with CYP2J2 inhibitors, implying that CYP2J2 provides cancer cells with a protective mechanism to increase their survival." (PMID 38001897, 2023). "CYP2J2 is highly expressed in malignant tumors, and a significant increase in CYP2J2 activity greatly promotes the proliferation of cancer cells and reduces the rate of apoptosis." (PMID 35154500, 2022). "NIR fluorescence bioimaging of CYP2J2 in cells was achieved in a range of human cancer cell lines (U251, HepG2, A549, and K562) within 1 h at physiological pH (λex = 633 nm, λem = 690–750 nm)." (PMID 34163615, 2021). "In fact, Jiang and co-authors characterized CYP2J2 expression in tissue samples obtained from 130 patients with different types of cancer." (PMID 33659048, 2021). "In this study, expression levels of CYP2J2 in various cancer types were determined using the Oncomine, the Gene Expression Profiling Interactive Analysis (GEIPA), DriverDBv3, UALCAN, and Tumor Immune Estimation Resource (TIMER) databases." (PMID 34258261, 2021). "An increasing body of evidence indicates that many medications, including those used in cancer treatment, are substrates for CYP2J2." (PMID 33659048, 2021). "CYP2J2 is also upregulated in numerous forms of cancer and has been detected in five human-derived malignant hematological cell lines, as well as in leukemia cells from peripheral blood and bone marrow in 86% of patients with malignant hematologic diseases." (PMID 34281173, 2021). "The data demonstrated that CYP2J2 plays an important role in the pathogenesis and progression of several types of human cancers." (PMID 33659048, 2021). "In line with this, selective inhibitors of CYP2J2 were reported to exhibit strong activity against human cancers in vitro and in vivo." (PMID 34281173, 2021). "Apart from the therapy of cancer, CYP2J2 also mediated the epoxidation of linoleic acid to form epoxidation of oleic acid (EOA) which can induce the mitochondria dysfunction then increased mortality of burn patients." (PMID 33682565, 2021). "The addition of recombinant adeno-associated viral vector- (rAAV-) mediated delivery of CYP2J2, exogenous EETs, or a selective 14,15-EET epoxygenase known as CYP102 F87V resulted in a high proliferation of cancer cells in vivo and in vitro." (PMID 31998435, 2020).
cancer (continued). "CYP2J2 protein and mRNA levels were found to be high in certain human cancer tissues and human-derived cancer cell lines." (PMID 31998435, 2020). "Overexpression of CYP2J2 or addition of exogenous EETs markedly accelerated proliferation and metastasis of cancer cells in vitro and in vivo." (PMID 22761738, 2012). "Our previous study showed that overexpression of CYP2J2 or additing exogenous EETs decreased apoptosis and increased cell proliferation in cancer cell lines and increased tumor growth and lung metastasis in a murine xenograft model." (PMID 22761738, 2012). "Using CYP2J2-expression cancer cell lines and a tumor xenografs model, we have shown that human CYP2J2 is posttranscriptionally regulated by let-7b and that the posttranscriptional regulation is responsible for the tumor-promotion function of CYP2J2." (PMID 22761738, 2012). "Results showed that CYP2J2 was highly expressed in the majority of cancer tissue samples compared with adjacent normal tissues." (PMID 22761738, 2012). "Western blot analysis showed that overexpression of let-7b significantly downregulated the expression of CYP2J2 in four cancer cell lines." (PMID 22761738, 2012). "Effects of the other members of let-7 family on CYP2J2 expression and cancer cell proliferation need further study." (PMID 22761738, 2012). "In recent publications, CYP2J2-derived EETs were found to play important roles in a host of processes related to cancer cell behavior and tumor pathogenesis." (PMID 22761738, 2012). "Our work also indicated that human CYP2J2 is posttranscriptionally regulated by let-7b, which results in the high expression of CYP2J2 protein in human carcinomas." (PMID 22761738, 2012). "CYP2J2 overexpression or addition of exogenous EETs protected human carcinoma cells from apoptosis by upregulating the antiapoptotic proteins, Bcl-2 and Bcl-xL, and by downregulating the proapoptotic protein, Bax." (PMID 22761738, 2012). "CYP2J2 inhibition has been shown to suppress the proliferation of cancer cells." (PMID 38966316, 2024). "Mechanistic studies demonstrated that high CYP2J2 expression strongly enhanced proliferation and reduced apoptosis in several cancers via the activation of kinase/Akt signaling pathways and increased the phosphorylation of epidermal growth factor receptor (EGFR)." (PMID 38001897, 2023). "Therefore, using CYP2J2 as a biomarker to detect the activity and localize CYP2J2 in vivo is of great significance for early diagnosis and treatment of cancer." (PMID 35154500, 2022). "CYP2J2 and CYP3A4 play a key role in the metabolism of cancer drugs known to cause cardiotoxicity." (PMID 33659048, 2021). "To determine whether CYP2J2 expression levels are correlated to the prognosis of cancer patients, we evaluated the prognostic value of CYP2J2 in cancer using GEPIA." (PMID 34258261, 2021). "Moreover, high and selective CYP2J2 expression was demonstrated in various human tumor tissue samples and cancer cell lines." (PMID 33659048, 2021). "It is reported that CYP2J2 is highly upregulated in various human carcinoma cell lines and CYP2J2 could promote human cancer metastasis and tumor cell growth." (PMID 33312341, 2020). "Additionally, studies reported that the cytochrome P450 2J2 (CYP2J2) is overexpressed in human cancer tissues." (PMID 33330047, 2020). "Interestingly, CYP2J2 is found to be upregulated in various cancers, and it plays a crucial role in cancer cell proliferation and human cancer metastasis." (PMID 33312341, 2020). "As well, both CYP2J2 overexpression and EETs treatment in cancer cells could stimulate cell proliferation, survival, migration, and invasion." (PMID 28030819, 2017). "CYP2J2 expression is elevated in human malignant tumors, such as esophageal, liver, breast, lung, and colorectal cancers, and high levels of EETs are detected in urine and blood of patients with these cancers." (PMID 25406731, 2014).
cancer (continued). "We have previously reported that CYP2J2 stimulates proliferation of carcinoma cells and protects human carcinoma cells from apoptosis; so it was of interest to evaluate the effects of overexpression of let-7b on cell proliferation and apoptosis when endogenous CYP2J2 was inhibited by let-7b." (PMID 22761738, 2012). "Transfection of carcinoma cell lines with let-7b and injection of pSilencer-let-7b producing mature let-7b in vivo decreased CYP2J2 protein expression and enzymatic activity, suggesting that CYP2J2 is posttranscriptionally negatively regulated by let-7b." (PMID 22761738, 2012). "The high levels of CYP2J2 in these cancers may help to explain some of the poor immunological function of these cells, and may point to the presence of a high degree of continuous immuno-suppression through this pathway." (PMID 22028915, 2011). "Therefore, CYP2J2 may be an important target to develop the effective therapeutic methods for cancers." (PMID 33312341, 2020). "Thus, the high expression of CYP2J2 protein in cancer tissues may result from the decreased expression of let-7b, at least in part." (PMID 22761738, 2012). "On the other side, CYP2J2 mediates the production of endogenous metabolites' epoxyeicosatrienoic acids (EETs) from arachidonic acid; both CYP2J2 and EET are involved in cancer settings." (PMID 39479643, 2024). "Additionally, aberrantly abundant expression of CYP2J2, an epoxygenase, were detected in a series of human cancer cell lines, and its inhibition by selective inhibitor could induce apoptosis in human cancer cells." (PMID 35887201, 2022). "Previous studies have found that Cytochrome P450 (CYP) monooxygenases, primarily Cytochrome P450 2J2 (CYP2J2), were involved in tumor progression and cancer drug resistance." (PMID 35800370, 2022). "Notably, CYP1B1, CYP2W1, CYP2J2, and, more recently, CYP4Z1 have been determined to have cancer-specific expression." (PMID 38001897, 2023). "While the level of CYP2J2 was not altered in our tumour tissue samples, sEH expression was significantly lower in carcinomas, suggesting different concentrations of cytoprotective EETs." (PMID 37175404, 2023). "miRNA-let-7b has been suggested to decrease the expression of CYP2J2 in several cancer cell lines but no data is available in cardiac cells." (PMID 32486275, 2020). "For instance, CYP2J2 and CYP2W1 were both found to have a higher level of expression in carcinoma cells and transformed tissues where they could have a role in the progression or treatment of cancers." (PMID 31258835, 2019). "We found high expression of CYP2J2 in human tumors, as well as in eight human-derived carcinoma cell lines, but not in adjacent normal tissues and nontumoral human cell lines." (PMID 22761738, 2012). "Other evidence suggests that CYP2J2 and EETs, which lead to phosphorylation of the epidermal growth factor receptor and the subsequent activation of downstream phosphoinositide 3-kinase (PI3K)/AKT and MAPK signaling pathways, suppresses apoptosis and up-regulates proliferation in carcinoma." (PMID 20187943, 2010).